IDO1 (indoleamine 2,3-dioxygenase 1)
Diseases named in the same sentence as IDO1 in open-access papers (continued):
Sharing a sentence is not in itself a finding about the gene and the disease.
melanoma (continued). "In melanoma, cancer cells release Wnt5a to induce IDO1 activity in dendritic cells, subsequently reducing the efficacy of PD-1 blockade therapy." (PMID 35011702, 2022). "Other groups showed that treatment with MEK inhibitor in melanoma patients increases Ido1 expression, and this is coherent with the known interplay between MAPK pathways and Ido-1 in dendritic cells." (PMID 36419183, 2022). "Since LCs are a promising target for cancer immunotherapy we aimed to investigate the expression of IDO1 in SLN LCs of patients with melanoma, correlating it with CD83 and with clinical features of patients." (PMID 35408802, 2022). "Using a melanoma model, it was shown that tumors expressing high levels of IDO1 present an enrichment of TAMs and selective inhibition of AhR decreases tumor progression, by inhibiting the immunosuppression mediated by IDO1." (PMID 36588678, 2022). "It has been reported that pDCs and dDCs express the tolerogenic enzyme IDO1 in SLN of patients with melanoma, suggesting a crucial role of this enzyme in melanoma tolerance." (PMID 35408802, 2022). "Abnormally activated IDO1/TDO pathway of tryptophan in melanoma cells contributes to a diversified peptidome landscape which facilitates immune recognition." (PMID 36003368, 2022). "Some years later, these IDO1+ cells had been identified as pDC by the specific marker BDCA-2 in SLN of patients with melanoma." (PMID 35408802, 2022). "IDO1 is highly expressed in multiple tumor types, including melanoma, lung cancer, pancreatic cancer, and renal cell carcinoma." (PMID 35571116, 2022). "Another skin derived DC subset, SLN FXIII+ dermal DCs (dDCs) express IDO1, probably induced by melanoma-derived TGFb-2, and able to transform peripheral DC into tolerogenic cells." (PMID 35408802, 2022). "In mouse melanoma, tumor endothelial cells upregulate IDO1 in response to the increased secretion of interferon (IFN)γ by CD40-stimulated immunotherapy, revealing a new immunosuppressive feedback mechanism." (PMID 34136377, 2021). "Given the influence of IDO1 on melanoma’s malignant phenotype, we next aimed to determine its expression in SK-Mel-28." (PMID 33806305, 2021). "In turn, BMS-986242 is another novel IDO1 inhibitor that was originally designed to treat various cancers, including melanoma and renal cell carcinoma (RCC)." (PMID 34201791, 2021). "In clinical researches, the expression of IDO1 has been found in various tumors such as breast cancer, melanoma, and bladder cancer, which inactivates surrounding immune cells in TME primarily through abnormalities of Trp metabolism." (PMID 35003126, 2021). "IDO1 is also broadly expressed in a wide spectrum of human tumors, including melanoma, gynecological cancers, colon cancer, and hematological malignancies, and its expression is associated with poor clinical outcome." (PMID 34148865, 2021). "Then, we applied 11C-l-1MTrp to longitudinally monitor whole-body IDO1 variations in immunocompetent melanoma-bearing mice treated with l-1MTrp plus either chemotherapeutic drugs or antibodies targeting PD-1 and CTLA4." (PMID 34148865, 2021). "Despite promising findings in murine models and human in vitro studies, a Phase III clinical study with the IDO1 inhibitor epacadostat in combination with pembrolizumab (anti-PD1) in melanoma was disappointing." (PMID 34177968, 2021). "It has been shown in both murine and human models that Wnt5a from melanomas affects the local DCs to express indoleamine 2,3-dioxygenase-1 (IDO1) that stimulates development of T regulatory cells (TRegs) through kynurenine." (PMID 32292402, 2020). "In a syngeneic mouse model using IDO1-overexpressing B16F10 melanoma cells, NTRC 3883-0 effectively counteracted the IDO1-induced modulation of L-tryptophan and L-kynurenine levels, demonstrating its in vivo target modulation." (PMID 33584686, 2020).
melanoma (continued). "High expression of IDO1 has shown a positive correlation with immune tolerance and poor prognosis in patients with melanoma, glioma, and esophageal cancer; this finding was, to some extent, consistent with our results." (PMID 33718118, 2020). "IDO1 is expressed in immunosuppressive DCs, and its expression is negatively correlated with survival in melanoma patients." (PMID 32532030, 2020). "Modulation of IDO1 activity in vivo was studied in a syngeneic mouse model of melanoma induced with mIDO1-overexpressing B16F10 cells." (PMID 33584686, 2020). "We therefore generated stable sublines of the B16F10 melanoma cell line overexpressing mouse IDO1 (B16F10-mIDO1)." (PMID 33584686, 2020). "Correlations between PARP1 overexpression in melanoma cells and presence of tumoral PD-L1 and IDO1 were observed (p = 0.04, and p = 0.0001, respectively)." (PMID 32380691, 2020). "Following the success of PD-1 and CTLA-4 checkpoint inhibitors in melanoma, attention has turned to other checkpoint proteins such as IDO1." (PMID 32090113, 2020). "Solid tumors such as melanoma, breast, lung, and colon cancers constitutively express the Trp degrading enzyme IDO1." (PMID 32477324, 2020). "The latest phase III trial ECHO-301 have reported that the combination of epacadostat (IDO1 selective inhibitor) and PD-1 inhibitor pembrolizumab did not provide any additional survival benefit compared to pembrolizumab alone in advanced melanoma patients." (PMID 32776284, 2020). "Although these important observations on IDO1, no data are available on TDO and angiogenesis and on its cooperation with IDO1 on melanoma progression." (PMID 32776284, 2020). "A metabolic enzyme that gained tremendous attention in melanoma therapy is IDO1 as phase 1–2 clinical trials were developed to use IDO1 inhibitors in combination to anti-PD1 therapy." (PMID 32509589, 2020). "In our study, we observed a strong correlation between high PARP1 and IDO1 expressions in mucosal melanomas." (PMID 32380691, 2020). "Cellular activity was determined by measuring inhibition of Trp-catabolizing activity in the human A375 melanoma cell line, which expresses IDO1 after stimulation with IFNγ." (PMID 33584686, 2020). "Tumors with combined PARP1 and IDO1 high expression correlated with worse overall and melanoma-specific survival (p = 0.015, 0.0034 respectively)." (PMID 32380691, 2020). "Expression of IDO1 played an important role on tumor migration and invasion in melanoma, bladder cancer and lung cancer." (PMID 31315643, 2019). "The expression of IDO1 in ovarian cancer, brain cancer, melanoma, and acute myeloid leukemia has been found to be a significant predictor of poor prognosis." (PMID 31391111, 2019). "This, too, is consistent with previous reports that IDO1 expression increases in response to IFNγ produced by CD8+ T cells within the tumor microenvironment in melanoma." (PMID 29805749, 2018). "Of interest, checkpoint inhibition was recently combined with IDO1 inhibition in advanced melanoma which apparently improved response rates over single-agent PD-1 blockade." (PMID 29805749, 2018). "Recent studies have reported the contribution of immune cells in the up-regulation of IDO1 in mouse melanoma model." (PMID 26895379, 2016). "It has been reported that up-regulation of IDO1 in metastatic malignant melanoma cells and metastatic pancreatic ductal adenocarcinoma cells was associated with an increased number of regulatory T cells (Tregs) and shorter survival." (PMID 26895379, 2016). "Consistently, studies in mouse tumor model have reported that up-regulation of immunosuppressive molecules such as IDO1 and B7-H1 in the melanoma cells is driven by CD8+ T cells." (PMID 26895379, 2016). "In line with this, IDO1 expression in human melanoma was found to correlate with T-cell infiltration." (PMID 25691885, 2015). "We therefore investigated whether the HH/GLI signaling pathway also contributes to IFNγ/STAT1 regulated IDO1 expression in melanoma." (PMID 39962447, 2025).
melanoma (continued). "We performed HPLC-MS measurements of the IDO1 substrate tryptophan and its immunosuppressive product kynurenine in conditioned media of human melanoma cells (WM35) treated with either HPI-1, vismodegib or the IDO1-specific inhibitor epacadostat with or without IFNγ." (PMID 39962447, 2025). "Numerous studies indicate that excessive activation of the Kynurenine Pathway (KP) is widely observed in lung cancer, gastrointestinal cancer, prostate cancer, glioma, melanoma, and pancreatic cancer, with a marked upregulation of IDO1, correlating with poor tumor prognosis." (PMID 40103267, 2025). "Increased expression of immunosuppression-related genes, including IDO1, was detected after downregulation of WARS without a change in the phosphorylation status of STAT1, whereas a strong correlation between the levels of IFN-γ and IDO-1 was found in different types of melanoma." (PMID 40108693, 2025). "Notably, melanoma has emerged as a key model for integrating tryptophan metabolism with cancer immunotherapy, particularly in clinical trials combining IDO1 inhibitors with PD-1/PD-L1 blockade." (PMID 40666095, 2025). "Besides, clinical trials combining IDO1 inhibitors with CTLA-4 blockade in melanoma patients reported toxicities, leading to the discontinuation of some studies." (PMID 41233805, 2025). "To address the possible role of endogenous, physiological oncogenic GLI activity, we performed RNA-interference (RNAi)-mediated GLI1 inactivation in human BRAFV600E mutated melanoma cells (WM35) and treated the cells with IL6 [75 ng/mL] for 18 h to activate IDO1 expression via STAT3." (PMID 39962447, 2025). "The role of IDO1 in melanoma is controversial due to variability in IDO expression." (PMID 40092297, 2025). "However, the key clinical trial on melanoma patients in Phase III using epacadostat (an IDO1 inhibitor) in combination with pembrolizumab (PD1 inhibitor) drugs, did not improve overall survival compared to placebo plus pembrolizumab." (PMID 40554511, 2025). "Therefore, we also explored any signs of melanoma progression in the 3D models by performing immunohistochemical staining for IDO-1 and Melan-A." (PMID 39062529, 2024). "In addition, IDO1-induced tryptophan depletion facilitates tryptophan-to-phenylalanine codon reassignment (W > F) in melanoma cells, leading to in-frame protein synthesis continues across tryptophan codons." (PMID 38273337, 2024). "Among these enzymes, IDO-1 is extensively upregulated in several cancer types, including melanoma." (PMID 39062529, 2024). "Higher IDO1 expression has been observed in breast cancer and other cancers, including colorectal cancer, esophageal carcinoma, cervical squamous cell carcinoma, melanoma, and pancreatic cancer." (PMID 38780888, 2024). "Although the enzymatic activity is inhibited, the stabilized IDO1 protein is tyrosine-phosphorylated and capable of associating the oncogene SHP-2 phosphatase, two early molecular events in the signaling of IDO1 that have been previously demonstrated to incite the progression of B16 melanoma cells." (PMID 38333210, 2024). "Additionally, in this study, as PAK4 expression was linked to immune cell infiltration, IDO1 expression was similarly correlated with PD-L1 expression and the infiltration of FOXP3-positive cells in melanoma." (PMID 39273017, 2024). "Additional evidence has highlighted that following disease progression, a subset of melanoma cells might also express IDO1." (PMID 38791968, 2024). "Another study also revealed an adverse tumor-promoting effect of IDO1 inhibition in melanoma." (PMID 38273337, 2024). "Several IDO1 small-molecule inhibitors are in clinical trials for advanced melanoma." (PMID 38937431, 2024). "Overall, IDO1 expression in both APCs and melanoma cells correlates with poor prognosis, and IDO enzymes appear to have an influence on the immune system in terms of recognizing melanoma cells and setting up an early response, thus promoting tumor immune evasion and cancer spread." (PMID 38791968, 2024).
melanoma (continued). "Interestingly, IDO-1 has been shown to be expressed in tumors from breast, esophageal carcinoma, colorectal cancer, cervical squamous cell carcinoma, melanoma, and pancreatic cancer, and is upregulated by IFN-γ." (PMID 38188364, 2024). "A correlation between IDO1 expression in melanoma cells and poor prognosis has been demonstrated." (PMID 38791968, 2024). "Given that the overexpression of IDO-1 and alterations in the Trp/Kyn ratio are observed across all stages of the disease, this presents an intriguing direction for employing these potential biomarkers in future melanoma diagnostics." (PMID 39062529, 2024). "Previous studies showed that Melanoma-derived Wnt5a promotes the transcriptional expression of IDO1 in nearby DCs by Wnt5a-β-catenin signaling and activates the PPAR-γ signaling pathway, culminating in enhanced IDO1 activity to establish an immunosuppressive microenvironment." (PMID 39424786, 2024). "In the SLN of patients with melanoma, IDO1 expression has been described on DCs." (PMID 38791968, 2024). "Therefore, melanoma cells acquire resistance to IDO1/PD1 dual blockade therapy by reducing the antigen diversity at the cell surface to inhibit effective T cell responses." (PMID 38273337, 2024). "Following a recent late‐stage clinical trial failure of Incyte (an IDO1 inhibitor) in combination with pembrolizumab (an anti‐PD1 antibody) in patients with advanced malignant melanoma, researchers are exploring the multiple and complex roles of IDO1 in disease." (PMID 38706741, 2024). "In addition, overexpression of IDO1 in monocytes and low activity of IDO1 in response to INFγ correlated with worse outcomes in melanoma patients." (PMID 36834531, 2023). "Using a preclinical mouse model of B16-F10 melanoma overexpressing IDO1 (B16IDO), authors demonstrated that IDO-expressing tumors have marked increases in Treg frequency and upregulated expression of FoxP3 in tumor infiltrating CD4+ T cells compared to B16WT-tumor bearing mice." (PMID 37876966, 2023). "Similarly, IDO1 promotes immune escape in multiple tumors such as melanoma, colon cancer, and glioma by regulating Tregs." (PMID 37252189, 2023). "To determine whether the released IFN-γ by activated iNKT cells played a role in the induction of IDO1 expression in melanoma cells, we co-cultured iNKT cells with A375 or WM 266-4 cells in the presence or absence of an anti-IFN-γ blocking antibody." (PMID 37444608, 2023). "In view of the unclear role of IDO1 in melanoma, we selected IDO1 for cell assay validation." (PMID 37305390, 2023). "IDO1, was initially observed in plasmacytoid-shaped cells within melanoma." (PMID 37716991, 2023). "Considering that our survival analysis shows that IDO1 is highly expressed in human melanoma with a good prognosis, the role of IDO1 in vivo may have a more complex mechanism, such as activation of the immune system." (PMID 37305390, 2023). "We tested whether IDO1 expressed by melanoma cells co-cultured with iNKT cells was enzymatically active." (PMID 37444608, 2023). "Moreover, other previous studies uncovered data on specific interplay between MEK signaling and Ido-1 activation in dendritic cells in tumor microenvironment and on activation of Ido-1 expression by MEK-inhibitors in melanoma patients." (PMID 36419183, 2022). "In our study, the observed small-size IDO1+ cells might correspond to dDCs and pDCs, while the large-size, observed in positive SLNs, may represent melanoma cells." (PMID 35408802, 2022). "The CD83 down-regulation and IDO1 expression might be induced by melanoma and represent a novel immuno-escape mechanism." (PMID 35408802, 2022). "IDO1 silencing in melanoma cells inhibited cancer cell proliferation and induced cell apoptosis." (PMID 35371054, 2022). "Interestingly, blocking glutamine metabolism also suppressed IDO1 expression in both cancer cells and myeloid-derived cells, leading to a marked decrease in kynurenine levels in a mouse melanoma model." (PMID 35011702, 2022).
melanoma (continued). "The failure of IDO1 inhibitors for melanoma therapy might be related to an enhanced TDO activity or an elevated expression of IL-4-induced gene 1, another tryptophan-metabolizing enzyme that induces immunosuppression by producing AHR ligands." (PMID 35311158, 2022). "However, other clinical data from different cohorts of melanoma patients confirm a biological rational for targeting Ido-1." (PMID 36419183, 2022). "Herein we aimed to investigate IDO1 expression in SLN LCs from patients with melanoma." (PMID 35408802, 2022). "It is likely that pro-inflammatory cytokines generated by the innate immune system in response to melanoma may indeed favor IDO1 expression in both melanoma cells and peri-tumoral DCs." (PMID 35408802, 2022). "Silencing of the IDO1 gene, using RNA interference, significantly reduced melanoma growth in-vivo." (PMID 34201791, 2021). "Melanoma-derived Wnt5a promotes the transcriptional expression of IDO1 in nearby DCs by Wnt5a-β-catenin signaling and activates peroxisome proliferator-activated receptor-γ (PPAR-γ) signaling pathway, culminating in enhanced IDO1 activity to establish an immunosuppressive microenvironment." (PMID 35003126, 2021). "Moreover, though the relation between Wnt1 and miR-122-5p was reported in the melanoma, the connection between IDO1 and miR-122-5p/Wnt1 in chondrogenic stimulated MSCs is reported for the first time in this study." (PMID 34956209, 2021). "Specifically, we highlight the development cycle starting from tracer synthesis (11C-l-1MTrp) and biomarker identification (IDO1 in the mesenteric lymph nodes (MLNs)) to biomarker validation in a mouse model of melanoma treated with different immunotherapy regimens." (PMID 34148865, 2021). "Notably, expression of IDO1 in tumor infiltrating leukocytes was considerably lower than that observed in tumor endothelial cells from agonistic CD40 mAb treated B16-F10 melanomas." (PMID 32231867, 2020). "Together, our data indicate that IDO1 is mainly expressed in tumor endothelial cells of B16-F10 and HCmel12 melanomas and that its expression can be further enhanced by agonistic CD40 mAb therapy and the associated IFNγ expression in the tumor microenvironment." (PMID 32231867, 2020). "TDO may directly modulate cancer cell function rather than immune suppression and can be considered as a target for melanoma progression together with IDO1." (PMID 32776284, 2020). "Subcutaneous injection of yeast microparticles containing an IDO1 siRNA was able to significantly delay melanoma tumor growth in vivo, compared to yeast loaded with only TRP2 peptides or IDO1 siRNA, suggesting a strong synergistic effect of the siRNA and TRP2 antigen." (PMID 32532030, 2020). "IDO1 is considered a negative prognostic factor in tumors because of its ability to induce an immune-suppressed environment despite the failure of a recent clinical trial using an IDO1-selective enzyme inhibitor in combination with an anti-PD1 antibody in advanced melanoma." (PMID 32817121, 2020). "Nevertheless, tumor endothelial cells are a main source of IDO1 in B16-F10 and HCmel12 melanomas, and IDO1 expression in tumor endothelial cells is likely to affect the perivascular microenvironment, which all tumor-infiltrating T-cells cross following trans-endothelial migration." (PMID 32231867, 2020). "Furthermore, upregulation of IDO1 expression has been observed within the TME and associated with inferior clinical outcomes in several tumor types, including melanoma, making IDO1 an attractive target for immunotherapy across a broad range of tumor types." (PMID 30894212, 2019). "Analysis in endothelial cells of patients with advanced melanoma showed that only 17 out of 43 patients have an increased IDO expression and only 2 of 43 patients were IDO1 and PD-L1 double positive revealing that IDO is not an appropriate target for the majority of melanoma patients." (PMID 31417567, 2019). "IDO1 overexpresses in many types of human malignancies, such as melanoma." (PMID 29932010, 2018).